FAT1 (FAT atypical cadherin 1)
Diseases named in the same sentence as FAT1 in open-access papers (continued):
Sharing a sentence is not in itself a finding about the gene and the disease.
tumor (continued). "Since FAT1 and NFкB (RelA) are independently known to promote pro-tumorigenic inflammation and upregulate the expression of HIF-1α/EMT/stemness in tumors, targeting the NFкB (RelA)-FAT1 axis may attenuate an important tumor-promoting pathway in GBM." (PMID 31992226, 2020). "Therefore, with the introduction of Fat-1 genes, high intracellular n-3 LC-PUFA levels delivered profound changes to the host animal related to cell proliferation and differentiation, inflammatory, as well as tumor formation." (PMID 32046209, 2020). "The identification of key players in HNSCC such as FAT1 and PI3K as regulators of the Hippo-YAP pathway, as well as the activation of YAP as a relevant oncogenic mechanism in head and neck cancer opens the way for the use of different therapeutic strategies targeting this pathway in this tumor type." (PMID 31817001, 2019). "While an increase in the expression of Cyclooxygenase (COX)-2, and reduced expression of the tumor suppressive 15-PGDH were observed in WT-mice throughout the experimental periods, the expression of Hydroxyprostaglandin dehydrogenase (15-PGDH) was preserved in Fat-1-TG-mice." (PMID 27528223, 2016). "In addition to other members of the PCDH family, PCDHGB7 is closely related to proteins such as Protocadherin Fat 1(FAT1), mutL homolog 1(MLH1), and fragile histidine triad diadenosine triphosphatase (FHIT), which have been shown to be involved in DNA mismatch repair and related to tumor stemness." (PMID 39949775, 2025). "However, the relationship between FAT1 and IFNs has not yet been reported, and whether the type I interferon signaling pathway is involved in FAT1-driven tumor regression still requires clarification." (PMID 39781458, 2025). "To investigate whether suppression of MIB2 expression mimics the effect of a loss of FAT1 on tumor cell growth, we suppressed expression of FAT1 or MIB2 using siRNA in Hela cells as well as in HNSCCs lacking or expressing FAT1 followed by evaluation of cell growth and EdU incorporation." (PMID 40478800, 2025). "Interestingly, we similarly observed that tumor-mimetic stiffness modulated the phenotype and function of blood endothelial cells (BECs); however, immunofluorescent staining detected no significant alteration in FAT1 expression in BECs cultured on substrates of different stiffnesses." (PMID 41230499, 2025). "In summary, the lack of FAT1 promotes EZH2 inactivation, affecting the EMT process in tumor cells, coordinating epigenetic changes, and maintaining the epithelial state." (PMID 38600608, 2024). "However, in one other tumour region, FAT1 did not contain a SCNA but instead showed evidence of CN-independent ASE, which might represent transcript repression favouring the expression of the parental allele subject to copy number loss in the other two regions." (PMID 37046093, 2023). "Recent data have not only shown that loss of FAT1 expression leads to increased YAP/TAZ activity and expression of YAP/TAZ target genes but also that increased YAP/TAZ activity is responsible for increased tumor growth, EMT, metastasis and resistance to therapy in tumors lacking FAT1." (PMID 40478800, 2025). "Absence of FAT1 dismantles the Hippo core complex, leading to YAP dephosphorylation and its translocation to the nucleus, where it interacts with TEAD to induce the expression of genes promoting tumor progression." (PMID 32674318, 2020). "We suggested that other biallelic inactivation of FAT1, TRIP12 and CYLD (as well as PTEN) could occur through promoter methylation of these four genes in the tumours showing only monoallelic inactivation (only LOH without somatic mutation or only somatic mutation without LOH)." (PMID 29416628, 2018).
cancer (172 papers, 2011 to 2026). A tumor composed of atypical neoplastic, often pleomorphic cells that invade other tissues. "Recent studies indicate that mutations in FAT Atypical Cadherin 1 (FAT1) contribute to drug resistance in cancer cells." (PMID 41362743, 2026). "Among the top KEGG pathway enrichments associated with both FAT1 knockdown and overexpression, the strongest common enrichment in terms of total gene numbers was the 'Pathways in Cancer' signature followed by the 'PI3K-Akt signaling pathway'." (PMID 40083689, 2025). "Recent studies have reported the roles of FAT1 and its mutations in immunoregulation and cancer treatment." (PMID 40672387, 2025). "Mutations in FAT1 are commonly observed in cancers, including squamous cell carcinomas of the head and neck, lungs, and cervix." (PMID 41256331, 2025). "FAT1—encoding a protocadherin family member—ranks among the most frequently mutated genes in human cancers." (PMID 41230499, 2025). "This suggests a mechanism in which FAT1 mutations promote tumorigenesis in cSCC and other cancers, but still, more research is needed to investigate this further." (PMID 39199674, 2024). "Subsequently, PLA2R, PCDH7, HTRA1 and FAT1 antigens were found to be positive in patients with malignancy-associated MN." (PMID 38686366, 2024). "The molecular and biochemical background of FAT1 mutations, aberrant expression and regulation in cancer is poorly understood." (PMID 36653435, 2023). "FAT1 mutations have been reported in various cancer types including glioblastoma, colorectal cancer and head and neck cancer." (PMID 36653435, 2023). "Four of the five NF2 mutations present were approximately clonal (cancer cell fraction >0.75), while two out of three FAT1, PTPRT, and EP300 mutations each were approximately clonal." (PMID 35288096, 2022). "We explored the relationship of FAT1 mutations with TMB owing to its important roles in predicting cancer immune response and clinical outcome." (PMID 35739249, 2022). "The potential impact of detecting or targeting FAT1 mutations on cancer treatment is also prospectively discussed." (PMID 35965328, 2022). "Still, it is imperative to further the knowledge regarding the impact of FAT1 mutations on cancer development at the molecular and therapeutic levels, as well as discover novel FAT1-targeted therapeutic strategies for personalized medicine." (PMID 35965328, 2022). "The TMB and immunotherapy dataset revealed that FAT1 mutations were observed in 10% of the samples, which is consistent with the findings from the pan-cancer analysis." (PMID 36517565, 2022). "FAT atypical cadherin 1 (FAT1) is among the group of genes that is most frequently mutated in many cancers." (PMID 35965328, 2022). "In many cancers, loss of FAT1 function promotes epithelial-mesenchymal transition (EMT) and the formation of cancer initiation/stem-like cells." (PMID 35965328, 2022). "FAT atypical cadherin 1 (FAT1) encodes protocadherin, one of the most frequently mutated genes in human cancers." (PMID 36517565, 2022). "We analyzed the mutational information of FAT1 in pan-cancer using cBioportal and found that FAT1 was mutated in more than 10% of 10 tumors, including HNSC and UCEC." (PMID 36517565, 2022). "FAT1 encodes a protocadherin, which is one of the most frequently mutated genes in human cancers and plays various functions." (PMID 36517565, 2022). "Mutation of FAT1 results in dysregulation of these signaling transductions, which potentially contributes to carcinogenesis and cancer progression." (PMID 35965328, 2022). "In the pan-cancer cohort, the association between FAT1 mutations and favorable ICI outcome was further validated (HR: 0.74, 95% CI: 0.58–0.96, P = 0.022)." (PMID 35739249, 2022).
cancer (continued). "Although a high FAT1 mutation rate has been identified in many types of cancer, its functions and clinical significance remain to be further elucidated." (PMID 35965328, 2022). "As a frequently mutated protein in cancer, several studies have examined FAT1 as a cancer prognostic biomarker." (PMID 35965328, 2022). "Loss of FAT1-mediated control of β-catenin signaling was subsequently shown to occur in some cancers with FAT1 mutations." (PMID 35647082, 2022). "The objective of this review is to summarize the potential functions of FAT1 and its mutations in cancer progression to facilitate the development of treatments for patients harboring this specific mutated or deleted protein." (PMID 35965328, 2022). "For 404, 614, 1,662, and 3,554, the four FAT1 hot mutation sites in all types of cancers in the COSMIC database, we observed a high mutation ratio in clinical OSCC tissues but also in matched adjacent normal tissues and leukocyte DNA of normal individuals." (PMID 35646625, 2022). "Mutations in FAT1 always generate an inferior survival outcome in several cancers, such as NSCLC25 and HNSCC26,27." (PMID 35739249, 2022). "This is interesting given that loss of function of FAT1 (by deletion or mutation) has been linked to promoting metastasis and is a relatively uncommon cancer gene." (PMID 34830758, 2021). "While FAT1 somatic variants are very frequent in every type of human cancer, constitutive variants have only recently been associated with congenital conditions, with a recessive mode of inheritance." (PMID 34202629, 2021). "The FAT1 gene encodes a cadherin-like protein, which is able to potently suppress cancer cell growth." (PMID 30657779, 2019). "The FAT1 gene is implicated in the squamous cell differentiation and encodes a cadherin-like protein that is able to suppress cancer cell growth in vitro and in vivo by binding ß-catenin and antagonizing its nuclear localization." (PMID 29416628, 2018). "Somatic mutations in tumor suppressor FAT1 have been linked to Wnt signaling, driving cancer development." (PMID 29141020, 2017). "Two of our 15 sequenced cancers had acquired nonsense mutations in FAT1, which encodes a large protocadherin that contains multiple transmembrane repeats." (PMID 24777035, 2014). "Given the critical role of Wnt/β-catenin signaling in regulating cell proliferation—a key functional alteration observed in FAT1-deficient cancer cells, we next examined whether this pathway is activated upon FAT1 loss in mLECs." (PMID 41230499, 2025). "FAT1 mutations are common in human cancers, predominantly occurring as nonsense mutations." (PMID 40672387, 2025). "FAT1 is among the group of genes that is most frequently mutated in many cancers." (PMID 39044272, 2024). "Loss of FAT1 binding capacity for the key classical WNT pathway protein β-Catenin was caused by loss of FAT1 expression in cancer and therefore resulted in β-Catenin translocation to the nucleus and downstream expression effects such as regulation of target genes MYC and Cyclin D1." (PMID 36653435, 2023). "A panel of differentially expressed proteins, stratified by FAT1 mutation status, were identified to be involved in the activation of growth factors and signaling pathways with potential effect on cancer cell proliferation, metastasis, angiogenesis, and immunomodulation." (PMID 35573184, 2022). "Interestingly, compared to FAT1 wild‐type cancer cells, the loss of FAT1 dramatically enhances the drug sensitivity of cancer cells to dasatinib, saracatinib (SRC inhibitors), and KN93 (CAMK2 inhibitor)." (PMID 35601657, 2022). "In addition, the association of FAT1 mutations with favorable ICI outcome was observed in a pan-cancer cohort." (PMID 35739249, 2022). "FAT atypical cadherin 1 (FAT1) is among the most frequently mutated genes in many types of cancer." (PMID 35965328, 2022).
cancer (continued). "FAT1 is one of the most frequently mutated genes in this cohort, in which truncating mutations account for >70% of all FAT1 mutations, in sharp contrast to other cancer types." (PMID 35646625, 2022). "Moreover, it has been recently shown that the loss of Fat1 promotes hybrid EMT state of cancer cells via CAMK2–CD44–SRC axis and EZH2–SOX2 axis, which upregulates the mesenchymal properties and maintains the epithelial characteristics, respectively." (PMID 35601657, 2022). "Further in-depth studies are needed, but FAT1 mutations may be a novel selection for enrolling cancer patients to receive immunotherapies." (PMID 35739249, 2022). "FAT1 expression or mutation has also been linked to cancer treatment sensitivity." (PMID 35965328, 2022). "In another ICI cohort, we could not fully validate the prognostic value of the signature because of insufficient coverage of the Memorial Sloan Kettering Cancer Center panel, but we observed a significant correlation of FAT1 mutation with longer OS." (PMID 35993362, 2022). "FAT1/4 mutations were related to better OS in pan-cancer patients treated with ICIs." (PMID 35965328, 2022). "According to the TCGA database, FAT1 is frequently mutated in many types of cancer." (PMID 34150758, 2021). "The FAT family consists of 4 genes (FAT1‐4), which have been linked to different cancers." (PMID 32533757, 2020). "We demonstrated aberrant FAT1 mRNA and protein expression in OSCC compared with non-cancer tissues, whereas loss-of-FAT1-function attenuates human primary SAS and metastatic HSC-3 OSCC cell viability, without affecting normal primary human gingival fibroblast cells." (PMID 31783581, 2019). "Alteration of FAT1 expression and function has been associated to several human cancers." (PMID 30416985, 2018). "Based on its frequent mutations and copy number loss in cancer, FAT1 has been hypothesized as a TSG." (PMID 26247464, 2015). "Results from the Cancer Genome Atlas project and the India Project conducted by the International Cancer Genome Consortium (India project team of the International Cancer Genome Consortium, 2013) showed that FAT1 is mutated in 20%-40% of HNSCC." (PMID 26247464, 2015). "Since elevated CIN is known to synergize with WGD to generate increased intratumour heterogeneity and escape from targeted therapeutic pressure, we also investigated whether FAT1 loss might enable WGD PC9 cells to accelerate cancer evolution and bypass targeted therapy treatment." (PMID 39738653, 2024). "In addition, FAT1 is one of the most frequently mutated genes in human cancers." (PMID 37211598, 2023). "Understanding the DNAH9 and FAT1 mutations may contribute to cancer surveillance and treatment." (PMID 35938006, 2022). "FAT1 inhibits cancer cell growth by binding β-catenin and preventing its nuclear localization, and its loss results in β-catenin stabilization and nuclear translocation, promoting oncogenic Wnt/β-catenin signaling 10,11,36." (PMID 41362743, 2026). "Genes such as PIK3CA, FAT1, FAT4, and CTNNB1 exhibit relatively similar mutation frequencies across both cancers, though slightly higher in SC for PIK3CA and FAT1/FAT4." (PMID 41419500, 2025). "Related work in TNBC cells showed that reducing FAT1 expression through proteasomal degradation serves to activate the Hippo pathway and promote cancer cell stemness and chemotherapy resistance." (PMID 40083689, 2025). "This approach showed enhanced antitumor activity when combined with CPI‐613 in murine models bearing mutant FAT1 head and neck tumors, offering a promising avenue for more effective and tailored cancer treatments." (PMID 40407216, 2025). "The role of FAT1 in both normal and cancer tissues has been extensively investigated since its initial discovery in Drosophila." (PMID 40407216, 2025). "Although FAT1's role has attracted considerable attention, its impact on cancer metabolism and treatment resistance remains poorly understood." (PMID 40407216, 2025).
cancer (continued). "Mutations in 376 genes, including FAT1, were significantly associated with increased TMB in various cancers, and FAT1 mutation characteristics were associated with favorable responses to immunotherapy." (PMID 40242237, 2025). "Other notable mutated cancer-related genes include PIK3CA (7%), CREBBP (6%), KMT2C (6%), KMT2D (6%), RB1 (5%), PTEN (5%), and FAT1 (5%), all of which are reported as “Tier 1” cancer-related gene mutations in the COSMIC Cancer Gene Census21." (PMID 40057511, 2025). "Several well-known cancer-associated genes (e.g. EP300, FAT1) have carcinogenic effect estimates in the statistical vicinity of one, yet they also exhibit strong signals of positive selection in ESSCs17." (PMID 41279109, 2025). "Consistent with other studies, our data highlight the importance of FAT1 and Hippo pathway dysregulation in genome instability, targeted therapy resistance and cancer evolution." (PMID 39738653, 2024). "The expression of the FAT1 gene increased in the high-grade group compared with the low-grade group and was differently expressed in 16 cancer species." (PMID 38167455, 2024). "In cancer biology, however, the effect of FAT1 on migration depends on the cancer type or context, as FAT1 either suppresses or enhances cancer cell migration and invasion." (PMID 37371091, 2023). "On the other hand, a number of studies report that FAT1 suppresses cancer cell migration and invasion, which is more consistent with the functions of a classical cadherin." (PMID 37371091, 2023). "To provide a more comprehensive picture of the molecular mechanisms underlying these effects, the studies we discuss are not limited to VSMCs; specifically, we include reports of FAT1 in cancer cells in which anti-migratory function has been described." (PMID 37371091, 2023). "For instance, FAT1 was considered a tumor suppressor gene or oncogene depending on the cancer types." (PMID 35836939, 2022). "In this study, we conducted a database search and found that two other tumor suppressor genes, NOTCH1 and FAT1, have a high nonsense mutation rate (NOTCH1: 19.62% and FAT1: 40.11%) in HNSCC mutation samples in the COSMIC database compared to other cancers." (PMID 36428516, 2022). "This study analyzed the relationship between FAT1 expression and 22 different types of immune cell infiltration in pan-cancer." (PMID 36517565, 2022). "Investigations from fields unrelated to cancer have yielded some interesting clues regarding FAT1’s effects on the immune regulatory system." (PMID 35965328, 2022). "We applied the immunological deconvolution method to observe the statistical correlation between FAT1 expression and the infiltration level of 22 immune cells in pan-cancer." (PMID 36517565, 2022). "Our first pan-cancer study provided a relatively comprehensive understanding of the oncogenic role of FAT1 in tumors." (PMID 36517565, 2022). "FAT atypical cadherin 1 (FAT1) is expressed as a transmembrane protein and has been investigated only in recent years for its role in human cancers." (PMID 35720420, 2022).